NTAQ1 (N-terminal glutamine amidase 1)
Description:
Mediates the side-chain deamidation of N-terminal glutamine residues to glutamate, an important step in N-end rule pathway of protein degradation. Conversion of the resulting N-terminal glutamine to glutamate renders the protein susceptible to arginylation, polyubiquitination and degradation as specified by the N-end rule. Does not act on substrates with internal or C-terminal glutamine and does not act on non-glutamine residues in any position. Does not deaminate acetylated N-terminal glutamine. With the exception of proline, all tested second-position residues on substrate peptides do not greatly influence the activity. In contrast, a proline at position 2, virtually abolishes deamidation of N-terminal glutamine.
Synonyms: C8orf32; WDYHV1; FLJ10204
Tractability: PROTAC: ubiquitination databases record sites on it.
Gene: Protein-coding gene on chromosome 8 (123,416,723 to 123,470,028, forward strand). Ensembl gene ENSG00000156795.
Subcellular location: Cytoplasm, cytosol; Nucleus
Subcellular location (Human Protein Atlas): Nucleoplasm; Vesicles
Gene Ontology:
Molecular function: protein binding; protein-N-terminal glutamine amidohydrolase activity; hydrolase activity, acting on carbon-nitrogen (but not peptide) bonds, in linear amides; protein-N-terminal asparagine amidohydrolase activity
Biological process: protein modification process
Cellular component: nucleoplasm; cytosol; nucleus
Genetic constraint (gnomAD): Loss-of-function variants: 16 observed, 22.99 expected, observed/expected ratio (o/e) 0.7, 90% interval 0.47 to 1.06. The upper end of that interval is the gene's LOEUF score, 1.06, which puts it in group 4 of 6, group 1 being the genes least tolerant of losing a copy. Missense variants: 252 observed, 240.7 expected, observed/expected ratio (o/e) 1.05, 90% interval 0.94 to 1.16. Synonymous variants: 104 observed, 86.12 expected, observed/expected ratio (o/e) 1.21, 90% interval 1.03 to 1.42.
Homologues: Orthologues: chimpanzee NTAQ1 (99% identical), macaque NTAQ1 (97% identical), dog NTAQ1 (93% identical), guinea pig NTAQ1 (88% identical), mouse Ntaq1 (83% identical), rat Ntaq1 (78% identical), zebrafish ntaq1 (64% identical), tropical clawed frog ntaq1 (59% identical), Drosophila melanogaster tun (44% identical), Caenorhabditis elegans R06C7.6 (33% identical).
Diseases named in the same sentence as NTAQ1 in open-access papers:
NTAQ1 is named in the same sentence as 2 diseases in open-access papers, as found by Europe PMC text mining. Sharing a sentence is not in itself a finding about the gene and the disease.
NTAQ1 shares sentences with these, for which no sentence is quoted: infection (1 paper); tumor (1).